CDH12 (cadherin 12)
Description:
Cadherins are calcium-dependent cell adhesion proteins. They preferentially interact with themselves in a homophilic manner in connecting cells; cadherins may thus contribute to the sorting of heterogeneous cell types.
Synonyms: BR-cadherin; CDHB
Tractability: Antibody: its Gene Ontology location is reachable by antibodies, with high confidence; UniProt places it where antibodies can reach, with medium confidence; UniProt predicts a signal peptide or a membrane-spanning region.
Gene: Protein-coding gene on chromosome 5 (21,750,673 to 22,853,344, reverse strand). Ensembl gene ENSG00000154162.
Subcellular location: Cell membrane
Subcellular location (Human Protein Atlas): Vesicles
Pathways (Reactome):
Cell-Cell communication: Adherens junctions interactions
Gene Ontology:
Molecular function: beta-catenin binding; cadherin binding; calcium ion binding
Biological process: adherens junction organization; calcium-dependent cell-cell adhesion; cell migration; cell morphogenesis; cell-cell adhesion mediated by cadherin; cell-cell junction assembly; cell adhesion; cell-cell adhesion; homophilic cell-cell adhesion
Cellular component: adherens junction; catenin complex; plasma membrane; membrane
Genetic constraint (gnomAD): Loss-of-function variants: 27 observed, 55.74 expected, observed/expected ratio (o/e) 0.48, 90% interval 0.36 to 0.67. The upper end of that interval is the gene's LOEUF score, 0.67, which puts it in group 2 of 6, group 1 being the genes least tolerant of losing a copy. Missense variants: 737 observed, 810.77 expected, observed/expected ratio (o/e) 0.91, 90% interval 0.86 to 0.97. Synonymous variants: 318 observed, 302 expected, observed/expected ratio (o/e) 1.05, 90% interval 0.96 to 1.15.
Homologues: Orthologues: chimpanzee CDH12 (99% identical), macaque CDH12 (99% identical), dog CDH12 (98% identical), pig CDH12 (97% identical), rabbit CDH12 (97% identical), guinea pig CDH12 (96% identical), rat Cdh12 (96% identical), mouse Cdh12 (96% identical), tropical clawed frog cdh12 (82% identical). Paralogues in human: CDH10 (60% identical), CDH6 (60% identical), CDH18 (57% identical), CDH9 (57% identical), CDH7 (56% identical), CDH20 (56% identical), CDH11 (55% identical), CDH8 (55% identical), CDH22 (49% identical), CDH24 (46% identical), CDH19 (45% identical), CDH5 (37% identical), and 21 more.
Diseases named in the same sentence as CDH12 in open-access papers:
CDH12 is named in the same sentence as 30 diseases in open-access papers, as found by Europe PMC text mining. Sharing a sentence is not in itself a finding about the gene and the disease. The quoted sentences say what the papers report.
bladder cancer (7 papers, 2021 to 2024). "Similarly, in bladder cancer, CDH12+ epithelial cell was associated with poor prognosis." (PMID 36313703, 2022). "It was also found that patients with CDH12-enriched bladder cancer had a poorer postoperative prognosis but a better prognosis with ICT." (PMID 39559360, 2024). "In conclusion, CDH12 enrichment stratified patients as a better predictor of prognosis than current bladder cancer subtypes." (PMID 39559360, 2024). "First, a new set of genetic expressions potentially predictive of low and high stages of bladder cancer was identified that includes Luminal, Luminal differentiation, Neuroendocrine differentiation, Normal Basal Intermediate, and Normal CDH12." (PMID 38203254, 2023). "Recently, a study reported that patients with CDH12-enriched bladder cancers have poor outcome of neoadjuvant chemotherapy, and that CDH12-enriched cancer cells exhibit aggressiveness and chemoresistance." (PMID 37355711, 2023). "Patients stratification by tumor CDH12 enrichment offers better prediction of outcome than currently established bladder cancer subtypes." (PMID 36313703, 2022). "In all settings, patient stratification by tumor CDH12 enrichment offers better prediction of outcome than currently established bladder cancer subtypes." (PMID 34385456, 2021). "In bladder cancer, CDH12+ epithelial cells colocalized with exhausted CD8+ T cells." (PMID 36313703, 2022). "In bladder cancer, fibroblasts were observed resided in close proximity to CDH12+ epithelial cells." (PMID 36313703, 2022).
colorectal cancer (6 papers, 2013 to 2023). A primary or metastatic malignant neoplasm that affects the colon or rectum. "CDH12 is highly expressed in tumor samples from patients with colorectal cancer or salivary adenoid cystic carcinoma and associated with metastasis and poor prognosis." (PMID 37355711, 2023). "Among them, CDH12, which encodes cadherin 12, has been linked to proliferation and invasion of colorectal cancer cells and salivary adenoid cystic carcinoma cells." (PMID 37355711, 2023). "CDH12 is expected to become a new diagnostic and prognostic marker and a novel target of the treatment of colorectal cancer." (PMID 24237488, 2013). "Although CDH12 has been reported in colorectal cancer cells and salivary adenoid cystic carcinoma cells to promote proliferation, migration and epithelial mesenchymal transition, little is known about the underlying molecular mechanism." (PMID 37355711, 2023). "CDH12 is an emerging potential biomarker that plays an essential role in tumorigenicity in colorectal cancer by promoting migration, invasion, adhesion, and angiogenesis." (PMID 38069216, 2023). "Specifically, in colorectal cancer, it has been suggested that CDH12 increases cancer cell migration by promoting epithelial‐mesenchymal transition via activation of the Snail transcription factor pathway." (PMID 35754128, 2022). "In this study, we investigated the expression of CDH12 and the role of CDH12 in prognosis of colorectal cancer (CRC) patients." (PMID 26762412, 2016). "In our present study, we demonstrated that CDH12 acts as an oncogene in colorectal cancer cell invasion and migration." (PMID 26762412, 2016). "In our research, we demonstrated the down-regulation of proliferation, invasion and migration ability in colorectal cancer cell lines by silencing CDH12 expression." (PMID 24237488, 2013). "We decided to investigate the relationship between CDH12 expression level and clinicopathologic variables in colorectal carcinoma (CRC) patients and to explore the functions of CDH12 in tumorigenesis in CRC." (PMID 24237488, 2013). "The expression levels of CDH12 in colorectal carcinoma tissues were detected by immunohistochemistry." (PMID 24237488, 2013). "Moreover, in the case of colorectal cancer, CDH12 affects the epithelial–mesenchymal transition (EMT), which is an important process in the pathogenesis of infertility and endometriosis." (PMID 38069216, 2023). "Our results showed that CDH12 promotes proliferation, migration, invasion, adhesion and angiogenesis, suggesting that CDH12 may be an oncogene in colorectal cancer." (PMID 24237488, 2013). "However, the function of CDH12 in colorectal cancer is unclear." (PMID 24237488, 2013).
breast carcinoma (4 papers, 2022 to 2025). "Moreover, we show that anastasis induces epigenetic de-repression of CDH12, the gene encoding cadherin 12 (CDH12), which in turn promotes proliferation and migration of breast cancer cells through activating ERK and CREB." (PMID 37355711, 2023). "Anastatic breast cancer cells also upregulate the cell adhesion protein cadherin 12 (CDH12) in vitro." (PMID 40555379, 2025). "Taken together, these results indicate that increased expression of CDH12 is essential for the enhanced malignancy of breast cancer cells after anastasis induced by chemotherapeutic drugs." (PMID 37355711, 2023). "Analysis of publicly available datasets revealed that breast cancer patients with high CDH12 expression exhibited worse progression-free survival, implying the association of CDH12 with breast cancer malignancy." (PMID 37355711, 2023). "Mechanistically, cadherin 12 (CDH12) is persistently upregulated in anastatic cells and promotes breast cancer malignancy via activation of ERK and CREB." (PMID 37355711, 2023). "Our work unveils anastasis and CDH12 as potential targets for preventing breast cancer relapse and metastasis following chemotherapy." (PMID 37355711, 2023). "In conclusion, we demonstrate that anastasis after exposure to chemotherapeutic drugs induces de-repression of CDH12 transcription, leading to enhanced malignancy in breast cancer cells." (PMID 37355711, 2023). "Our results unveil CDH12 as a positive regulator for post-chemotherapy relapse and metastasis of breast cancer." (PMID 37355711, 2023). "Our data demonstrate that after exposure to chemotherapeutic drugs, breast cancer cells that survive from executioner caspase activation acquire enhanced proliferation and migration through de-repression of CDH12 transcription and the subsequent activation of ERK/CREB signaling." (PMID 37355711, 2023). "CDH1, CDH2, and CDH12 exhibited strong intensities in cell nuclei in breast cancer samples." (PMID 36315446, 2022). "The most upregulated genes, on the other hand, are less abundant (TPM < 100), such as SERPINI2, which encodes a protease inhibitor protein; CDH12, which, despite its role in cell adhesion and proliferation, is not commonly studied in breast cancer; and WDR, a gene about which little is known." (PMID 36982287, 2023). "In this study, we show that upregulated expression of CDH12 and the subsequent activation of ERK/CREB signaling are responsible for the increased proliferation and migration of anastatic breast cancer cells." (PMID 37355711, 2023). "CDH12 staining intensities were negative (one case), weak (three cases), moderate (one case), and strong (seven cases) in breast cancer samples." (PMID 36315446, 2022). "However, in breast cancer cells, CDH12 activated ERK not PKA." (PMID 37355711, 2023).
endometriosis (4 papers, 2022 to 2025). The growth of functional endometrial tissue in anatomic sites outside the uterine body. "For Inhalants LU, there was a lead SNP located in the CDH12 gene, encoding a protein that was associated with infertility and endometriosis in females." (PMID 40736093, 2025). "This study aimed to elucidate on the diagnostic potential of CDH12 in patients with endometriosis and infertility." (PMID 40506938, 2025). "One such molecule, Cadherin 12 (CDH12), has been implicated in the pathogenesis of endometriosis and infertility." (PMID 40506938, 2025). "Moreover, testing cadherin 12 levels in the plasma can be an idea that is complementary to our work because of the higher diagnostic potential of this biological material in terms of endometriosis as well as infertility." (PMID 36141853, 2022). "CDH12 plasma concentrations were analyzed in relation to factors such as fertility status, age, day and phase of cycle, stage of endometriosis, and the presence of ovarian cysts." (PMID 40506938, 2025). "Previously, we described the potential role of CDH12 in the pathogenesis of endometriosis by investigating samples of peritoneal fluid from patients with endometriosis compared to controls, but there are no more examples of such articles." (PMID 40506938, 2025). "The study of CDH12 concentration using the method proposed in this article and the previously published results on CDH12 content in the peritoneal fluid of women with endometriosis are among the first to reveal the contents of CDH12 in human body fluids." (PMID 38069216, 2023). "Then, the different groups of patients for the statistical significance analysis of CDH12 concentration differences were selected based on their stage of endometriosis and infertility factor." (PMID 36141853, 2022). "We aimed to determine if there were possible statistically significant differences in CDH12 concentrations related to age, infertility, stage of endometriosis, presence of ovarian cysts, day of the cycle, and phase of the cycle." (PMID 36141853, 2022). "Although our findings did not strongly support the potential of CDH12 as a marker for endometriosis or infertility, its biology, which is closely linked to the pathogenesis of both conditions, warrants further studies." (PMID 40506938, 2025). "Similarly to our previous work, we also aimed to relate CDH12 concentration in peritoneal fluid to clinical factors such as fertility status, age, phase of the cycle, stage of endometriosis, and presence of ovarian cysts." (PMID 40506938, 2025). "In our material, the results did not confirm the direct diagnostic potential of CDH12 in patients with endometriosis, despite using a novel and more sensitive method of its evaluation as well as of using samples of both plasma and peritoneal fluid." (PMID 40506938, 2025). "Even considering that endometriosis might be responsible for a significant proportion of the female factor of infertility, we find this result noteworthy as it might point to some endometriosis-independent mechanisms of infertility involving CDH12." (PMID 40506938, 2025). "Additionally, in a study group of patients with confirmed endometriosis, we observed a significant positive correlation of CDH12 concentrations with patients’ age." (PMID 40506938, 2025). "Cadherin 12 (CDH 12) can play a role in the pathogenesis of endometriosis." (PMID 36141853, 2022). "It is noticeable that CDH12 is most likely an adjunctive “chainlink” rather than a primary driver of endometriosis." (PMID 40506938, 2025). "It has been shown that CDH12 plays a role in cancer progression of colorectal cancer in a mechanism including epithelial–mesenchymal transition (EMT), the involvement of which in the development of endometriosis has also been established." (PMID 40506938, 2025).
endometriosis (continued). "Previously, we also showed statistically significant differences in CDH12 concentrations in peritoneal fluid among patients with endometriosis and infertility compared with controls without these conditions." (PMID 40506938, 2025). "Cadherin 12 can possibly play a role in the pathogenesis of infertility, both in women with and without endometriosis." (PMID 36141853, 2022). "The aim of this study was to compare the levels of cadherin 12 in the peritoneal fluid between women with and without endometriosis." (PMID 36141853, 2022). "The aim of this study was to measure the concentration of CDH12 in plasma and peritoneal fluid samples collected from women with and without endometriosis using the optical method of SPRi and to examine potential interrelations between the studied group and patients’ characteristics." (PMID 40506938, 2025). "We plan to study the possible differences in CDH12 concentrations between those patients diagnosed with primary infertility in comparison with secondary infertility in general but also among patients with and without endometriosis." (PMID 36141853, 2022). "Although there are no specific reports on the potential negative effect of cadherin 12 on the fertility of patients with endometriosis, there can be multiple potential mechanisms in which different cadherins may potentially impact fertility." (PMID 36141853, 2022). "There are no publications regarding the exact role of CDH12 in the pathogenesis of endometriosis and infertility, nor are there any studies regarding the concentrations of this cadherin in the various biological materials collected from patients diagnosed with endometriosis." (PMID 36141853, 2022). "However, it can possibly play a role in the pathogenesis of infertility, both in women with and without endometriosis, resulting in statistically significant differences in CDH12 concentrations in the peritoneal fluid between these two groups, compared with fertile women." (PMID 36141853, 2022). "A direction for future research in this field might be an evaluation of differences in CDH12 concentrations, comparing patients diagnosed with primary infertility versus those with secondary infertility overall, as well as comparing patients with endometriosis versus those without." (PMID 40506938, 2025).
schizophrenia (4 papers, 2018 to 2024). A major psychotic disorder characterized by abnormalities in the perception or expression of reality. "CDH7 and CDH12 have been associated with bipolar disorders and CDH18 was found to be associated with schizophrenia." (PMID 39570883, 2024). "Moreover, a group of cadherins, CDH7, CDH12, CDH18 and PCDH12, are reported to be associated with bipolar disease and schizophrenia." (PMID 30148849, 2018).
bipolar disorder (3 papers, 2019 to 2024). A disorder of the brain that causes unusual shifts in mood, energy, activity levels and the ability to carry out day-to-day tasks. "Suggestively significant SNPs for brooding regulated brain expression level of CDH12, which result corroborates the genetic relationship of rumination phenotypes with bipolar depression and extends it to other disorders." (PMID 30886212, 2019).
Infertility (3 papers, 2022 to 2025). "Yet, the sample size allowed the detection of significant associations between CDH12 levels and infertility as well as patients’ age, indicating adequate sensitivity for biologically relevant effects." (PMID 40506938, 2025). "Among these, we confirmed significantly lower peritoneal fluid concentrations of CDH12 in patients with infertility as compared to fertile ones (14.772 ng/mL vs. 22.179 ng/mL, p < 0.05)." (PMID 40506938, 2025). "Considering our clinical material, the significant, yet still relatively weak, correlation between CDH12 concentrations and age requires further study, especially focusing on different types of infertility." (PMID 40506938, 2025). "Nevertheless, we found statistically significant differences for CDH12 peritoneal fluid concentrations between fertile and infertile women." (PMID 40506938, 2025). "There were statistically significant differences in CDH12 concentrations in terms of infertility and primary infertility (p = 0.009154; p = 0.009866, respectively)." (PMID 36141853, 2022).
colon cancer (2 papers, 2016 to 2022). "For example, overexpression of the cancer-specific cadherin-12 (CDH12) variant, a subtype of the N-cadherin family, can be generated by somatic LINE-1 insertion and induces migration and invasion of colon cancer cells by targeting the transcription factor, Snail." (PMID 36142830, 2022). "We analyzed the expression of CDH12 in seven colon cancer cell lines by using qRT-PCR." (PMID 26762412, 2016). "In this article, we presented the clinical significance of CDH12 in CRC patients’ specimens and elucidated its preminent influence on colon cancer cell proliferation as well as invasion." (PMID 26762412, 2016). "However, role of CDH12 in colon cancer is still largely unknown." (PMID 26762412, 2016).
myocardial infarction (2 papers, 2022). Gross necrosis of the myocardium, as a result of interruption of the blood supply to the area, as in coronary thrombosis. "A Study about myocardial infarction revealed overexpression of CDH2, CDH12, PCDH17, and PCDH18 in myocardial infarction vascular smooth muscle cells compared with controls." (PMID 35480311, 2022). "Overexpression of CDH12 and CDH26 might be related to myocardial infarction and progression of atherosclerosis." (PMID 36539828, 2022).
non-small cell lung carcinoma (2 papers, 2013 to 2019). A group of at least three distinct histological types of lung cancer, including non-small cell squamous cell carcinoma, adenocarcinoma, and large cell carcinoma. "CDH12 plays an important role in non-small-cell lung cancer(NSCLC) geneses, resulting from that the mutations of CDH12 and other PRAME family members were equally distributed among tumors of different grades and stages." (PMID 30972101, 2019). "This indicates that CDH12 acts as a tumor suppressor gene in the non-small-cell lung cancer." (PMID 24237488, 2013).
asthma (1 paper, 2022). "CDH12 expression is positively modulated by the chemotactic factor CCL2,53, 54 whose levels increases in blood and airway smooth muscle from asthma patients compared to healthy controls." (PMID 35754128, 2022).
colorectal tumor (1 paper, 2022). "Previous research implied that CDH12 might be influential in colorectal tumor metastasis." (PMID 36315446, 2022).